IL33 (interleukin 33)
Diseases named in the same sentence as IL33 in open-access papers (continued):
Sharing a sentence is not in itself a finding about the gene and the disease.
influenza infection (continued). "In the lung of mice, group 2 ILCs are activated in response to IL-33 following influenza infection and subsequent immune-mediated tissue damage." (PMID 28931041, 2017). "We here showed that during primary influenza infection and particularly during secondary pneumococcal pneumonia following influenza infection, lung levels of IL-33 gradually increased in both WT and st2−/− mice." (PMID 23483993, 2013). "The production of IL-5 by ILC2 is in part regulated by NKT cells and IL-33 produced by this cell type during the recovery phase of influenza infection." (PMID 24068930, 2013). "In mice models of influenza infection, exogenous IL-33 inoculation could enhance recruitment of dendritic cells (DCs), increase secretion of pro-inflammatory cytokine IL-12, and prime cytotoxic T-Cell responses, facilitating viral clearance." (PMID 38704386, 2024). "IL-33 may protect against influenza by orchestrating Th1/Th2 paradigm and so maintaining a fine balance of pro-inflammatory pathogen clearance and anti-inflammatory tissue repair." (PMID 38704386, 2024). "Besides, endogenous IL-33 release, within 24 h, after administration of alum-adjuvanted nasal influenza vaccine, induced higher IgA Ab production via enhancing Ag presentation on DCs and promoting ILC2 activation." (PMID 38704386, 2024). "IL-33 production is induced in influenza infected epithelial lung cells that in combination with IL-18, bind to their respective receptors (IL-18R and ST2) on regulatory T cells (Treg) and/or innate lymphoid cells (ILC) to promote lung tissue repair and inflammation control." (PMID 35479098, 2022). "Moreover, authors observed a correlation between IL-17A, IL-33, and amphiregulin in nasal washes of human influenza-infected infants." (PMID 35327516, 2022). "IL-33 was shown to be induced by IL-17A in γδ T cells in a mouse model of influenza infection." (PMID 35479098, 2022). "Indeed, this is illustrated in neonatal influenza infection, where a rapid γδ T cell IL-17A response is generated in the lung, which induces IL-33 in epithelial cells, leading to a pro-repair Areg response from ILC2 and Tregs." (PMID 33936115, 2021). "Intranasal vaccination with the IL-18 and IL-33 adjuvanted recombinant influenza vaccine significantly enhanced antigen-specific antibody responses in systemic compartments and mucosal sites and increased mouse survival during lethal influenza challenges." (PMID 33430259, 2021). "The IL-33/IL-17A repair axis may also operate in human infants, as nasal aspirates from children with mild influenza show positive correlations between IL-17A and IL-33 levels and also between IL-17A and Areg levels." (PMID 33936115, 2021). "Furthermore, the release of IL-33 was involved in the protective immunity against influenza virus infection which is induced by the intranasal administration of HP-β-CD-adjuvanted influenza split vaccine." (PMID 32210964, 2020). "Next, to confirm whether endogenous IL-33 influenced CTL responses against influenza infection, IL-33+/− and IL-33−/− mice were infected with the influenza virus." (PMID 31509992, 2019). "Though there have been some studies on the role of IL-33 in lung tissue damage or recovery, whether IL-33 enhances or exacerbates antiviral immunity during influenza infection remains unclear." (PMID 31509992, 2019). "IL-33 is a cytokine that is produced and released upon influenza infection." (PMID 31509992, 2019). "NKT cells themselves have been shown to be a source of IL-33 during influenza infection." (PMID 31354734, 2019). "This evidence may suggest that the IL-17/IL-33/amphiregulin axis may serve as a potential therapeutic target that is specifically important in cases of influenza infection in neonates." (PMID 31337278, 2019). "Although these findings may suggest that expression changes of these genes are difficult to detect in total lung, alternatively IL‐33‐driven Th2 cytokine production may be suppressed during influenza infection." (PMID 29762870, 2019).
influenza infection (continued). "Thus, our findings suggest a role of exogenous IL-33 in the antiviral immune response against influenza infection." (PMID 31509992, 2019). "Furthermore, Tsunoda and colleagues reported that IL-33 is able to act as a mucosal vaccine adjuvant by enhancing protective immune responses against influenza infection." (PMID 31509992, 2019). "The dysregulation of the antiviral immune response can also be seen in influenza infection, in which IL-33 driven secretion of IL-13 by ILC2 cells contributes to airway hyperactivity and may exacerbate disease in asthmatic individuals." (PMID 29552008, 2018). "Hence, the ST2/IL-33 pathway is dispensable for influenza-induced MCp recruitment to the lung." (PMID 30337928, 2018). "Influenza and RSV infection each stimulate IL-33 production from lung macrophages, which in turn activates ILC2s." (PMID 36032072, 2022). "Analyzing the cell response, the authors found that IL-18 and IL-33 were able to induce high-avidity CD8+ cytotoxic lymphocytes, thus sustaining those cytokines as useful adjuvants of effective mucosal influenza vaccines." (PMID 35327516, 2022). "Conversely, infection with influenza and RSV infection each stimulate IL-33 production from lung macrophages, which in turn activates ILC2s." (PMID 36032072, 2022). "Epithelial cell or myeloid cell derived IL-25, IL-33, and TSLP can promote an ILC2 response after allergen challenge, helminth exposure or influenza infection." (PMID 31354734, 2019). "Thus, we investigated whether exogenous IL-33 affects CTL responses against influenza infection." (PMID 31509992, 2019). "To address this question, we stained lymph nodes on day 2 of influenza infection with antibodies against CD169, IL-1β, IL-18, and IL-33." (PMID 29249358, 2018). "Using Rag2-deficient mice, the significance of innate immune cells being induced by the IL-33/ST2 pathway has been shown by intranasal IL-33 injections and influenza infection." (PMID 30337928, 2018). "Intranasal administration of IL-33 was shown to increase, in lung, the numbers of innate lymphoid cells, eosinophils, and dendritic cells that, in turn, are able to activate CD8+ T-cell responses against influenza infection." (PMID 35327516, 2022). "Their results showed that a reduction in IL-33 during superinfection correlated with a negative outcome, in contrast with what was seen during normal Influenza infection, and, more importantly, an improved bacterial clearance after restoration of IL-33." (PMID 35327516, 2022). "Children with influenza had elevated levels of IL-33, which positively correlated with levels of IL-17A but not with IFN-γ." (PMID 36061377, 2022). "Collectively, these results reveal that c-kit+ ILC2 interaction with IL-33 producing NKT and AM leads to abundant production of IL-5 by ILC2 and accounts for the accumulation of eosinophils observed during the recovery phase of influenza infection." (PMID 24068930, 2013). "To determine the possible impact of ST2 on pulmonary inflammation during influenza infection, we measured lung levels of cytokines (IFN-γ, TNF-α, IL-1β, IL-6, IL-10, IL-33, IL-13, IL-5) and chemokines (KC, MIP-2) at 3, 8 and 14 days following influenza inoculation." (PMID 23483993, 2013). "Furthermore, IL-33 largely contributed to the induction of Ag-specific IgA Ab production by the alum-adjuvanted influenza vaccine without Ag-specific IgE Ab production." (PMID 34460865, 2021). "Furthermore, IL-33 contributed to IgE Ab production when administered with OVA but not in response to the split influenza vaccine." (PMID 34460865, 2021). "However, absence of either TLR3 or ST2 alone, or blocking IL-33 in Tlr3−/− mice did not influence the massive influenza-induced recruitment of MCp to the lung, implicating that other pathways are involved in this process." (PMID 30337928, 2018). "The same authors could not detect IL-33 protein in poly(I:C) stimulated or influenza infected epithelial cells, in agreement with our results." (PMID 28127565, 2016).
influenza infection (continued). "However, influenza infection of monocytes did not induce production of IL-10, IL-12 or IL-33 (data not shown)." (PMID 22238612, 2012). "Furthermore, neutralization of IL-33 in Tlr3−/− mice could not abrogate the influenza-induced influx of mast cell progenitors to the lung." (PMID 30337928, 2018). "Although these results may seem counter-intuitive, the activation of the TLR3- or the IL-33/ST2 pathways alone triggered only a few-fold increase in lung MCp, which is by far not as impressive as the massive recruitment of MCp to the lung induced by influenza infection." (PMID 30337928, 2018). "However, in the present study both Tlr3- and Il1rl1-deficient mice had an intact recruitment of MCp to the lung in response to the influenza infection and blocking the IL-33/ST2 pathway in Tlr3−/− mice could not either abrogate the influx." (PMID 30337928, 2018). "Our results show that exogenous IL-33, but not endogenous IL-33, increased the recruitment of CD8+ T-cells into lungs following influenza infection." (PMID 31509992, 2019).
systemic lupus erythematosus (41 papers, 2008 to 2026). An autoimmune multi-organ disease typically associated with vasculopathy and autoantibody production. "Conclusively, nucleic acid–containing IC stimulation of SLE neutrophils recapitulates typical lupus NETosis and is associated with increased IL-33 expression." (PMID 34554930, 2021). "This study is aimed at exploring the relation between IL-33 single-nucleotide polymorphisms (SNPs) and the risk of systemic lupus erythematosus (SLE)." (PMID 30984790, 2019). "Another study also reported that IL-33 contributes to kidney fibrosis associated with systemic lupus erythematosus (SLE)." (PMID 30405626, 2018). "MRL/lpr lupus-prone mice treated with anti-IL-33 antibodies had reduced renal inflammation and serum autoantibodies." (PMID 39337564, 2024). "Conversely, the effect of early IL-33 administration in lupus-prone NZB/W F1 mice from weeks 6 to 12 significantly reduced proteinuria and mortality." (PMID 35328556, 2022). "This goes in line with studies performed in lupus patients, where increased serum levels of IL-33 have been shown to correlate with autoantibody levels." (PMID 35328556, 2022). "Mouse studies mirror discoveries made in humans as treatment of IL-33 inhibitory antibodies alleviated lupus symptoms in MRL/Lpr mice." (PMID 35444658, 2022). "Early IL-33 administration in lupus prone NZB/W F1 mice was shown to induce regulatory B cells and reduce autoantibody levels." (PMID 35069220, 2021). "Anti–IL-33 and/or aST2L antibodies are currently under clinical development; in a preliminary report, administration of anti–IL-33 antibody in MRL/lpr lupus–prone mice reduced anti-dsDNA and IC levels, kidney inflammation, and proteinuria." (PMID 34554930, 2021). "IL-33–bearing NETs infiltrating lupus end organs such as the kidneys and skin suggest they play an important role in regulating local autoimmune inflammation and tissue injury." (PMID 34554930, 2021). "Contrastingly, in a previously published study, antibody-mediated IL-33 neutralization suppressed disease in lupus prone mice along with an increase in Tregs and reduced IL-17 levels." (PMID 35069220, 2021). "IL33-silenced neutrophil-like cells cultured under lupus-inducing conditions generated NETs with diminished interferogenic effect." (PMID 34554930, 2021). "Our findings suggest that NET-complexed IL-33 from IC-treated lupus neutrophils drives IFN-α production by pDCs." (PMID 34554930, 2021). "Another study reported that upregulation of the IL-33/ST2 signaling pathway in case of systemic lupus erythematosus (SLE) promoted renal tubular cell injury and fibrosis primarily through renal EMT." (PMID 35046838, 2021). "Nevertheless, this study provides new evidence of the previously-unexplored disease-protecting roles mediated by IL-33 in delaying lupus onset." (PMID 33182616, 2020). "In this study, we determine the impact of intraperitoneal IL-33 treatments in young lupus, NZB/W F1 mice." (PMID 33182616, 2020). "Of note, it would be interesting to study the therapeutic impact of IL-33-induced M2 macrophages in lupus." (PMID 33182616, 2020). "Over the last several years, several studies have suggested that IL-33 and sST2 are involved in immune diseases such as systemic lupus erythematosus and atopic dermatitis." (PMID 26677348, 2015). "In systemic lupus erythematosus, elevated serum IL-33 was reported in clinical patients and correlated with their disease activity." (PMID 26675669, 2015). "Disrupting IL-33 pathway resulted in reduced serum anti-dsDNA levels, alleviated proteinuria, and attenuated lupus nephritis in lupus-prone mice." (PMID 26675669, 2015). "Interestingly, the role for cleaved IL-33 alarmin decorating NETs in human systemic lupus erythematosus, linking neutrophil activation, type I IFN production and end-organ inflammation has been demonstrated." (PMID 35408954, 2022).
systemic lupus erythematosus (continued). "Clinical results regarding the serum levels and roles of IL-33 in systemic lupus erythematosus (SLE) patients are conflicting, possibly due to issues of detection efficacy related to the heterogeneity of SLE patient cohorts in terms of disease activity and stage, treatment, and genetic background." (PMID 36291105, 2022). "Herein, driven by our striking finding of extracellular IL-33 complexed with NETs in lupus-afflicted tissues, we reasoned that NETting neutrophils may represent an important source of IL-33 alarmin contributing to excessive type I IFN." (PMID 34554930, 2021). "Our data are in line with findings implicating NET protease–processed IL-1β in gout attacks and of neutrophil protease-generated IL-33 in acute lung injury, pointing to neutrophil proteases generating NET-associated IL-33 with high interferogenic activity in the context of lupus." (PMID 34554930, 2021). "Additionally, an M2 macrophage signature was also induced implying a regulatory role of IL-33 in lupus onset." (PMID 35069220, 2021). "Overall, the findings in this study revealed the novel effect of IL-33 in suppressing lupus onset in young NZB/W F1 mice, presumably through the protective anti-dsDNA IgM antibodies, IL-10-expressing Breg cells, and upregulation of alternatively-activated M2 macrophage-genes." (PMID 33182616, 2020). "Blocking IL-33 activity in lupus MRL/lpr mice resulted in disease improvement." (PMID 33182616, 2020). "In the present study, we examined the biologic effect of IL-33 in young lupus-prone NZB/W F1 mice." (PMID 33182616, 2020). "In animal models of the disease, the administration of a monoclonal antibody against IL-33 to lupus-prone MRL/lpr mice reduced the deposition of immune complexes and the severity of nephritis, affecting the titre of anti-dsDNA antibodies and the level of inflammatory cytokines." (PMID 29422069, 2018). "In addition, in a mouse systemic lupus erythematosus (SLE) model, blockade of IL-33 could prevent the progress of SLE, which was associated with expansion of Tregs and MDSCs, and suppression of Th17 cells." (PMID 27007054, 2016). "Importantly, we implicate neutrophil proteases for the production of cleaved interferogenic IL-33 isoforms on lupus NETs, thus suggesting that interference with IL-33 maturation and/or signaling could be therapeutically exploited." (PMID 34554930, 2021). "In the lupus-prone model of MRL/Lpr mice, anti-IL-33 treatment from weeks 14 to 20 significantly reduced mortality and lessened serum anti-dsDNA levels and circulating ICs." (PMID 35328556, 2022). "IL-33–decorated chromatin structures were also detected in lupus-affected dermis (corroborated by H&E staining), contrary to healthy skin, which exhibited no inflammation or IL-33 expression." (PMID 34554930, 2021). "Moreover, as the role of IL-33 has only been studied in MRL/lpr mice, the use of other lupus animal models can verify our postulation." (PMID 33182616, 2020). "In fact, no data on the expression of IL-1R4 in the cells and tissues of patients with SLE are available, and no study on lupus-prone mice knockout (KO) for IL-33 or IL-1R4 genes has so far been conducted." (PMID 29422069, 2018). "IL-33 exhibits myeloid cell chemoattractant properties, thus it might also attract neutrophils to orchestrate a neutrophil/NETs IL-33/IFN-α feedback loop within lupus-inflamed kidneys." (PMID 34554930, 2021). "Finally, if IL-33 abolishes NET protection extracellularly, it is possible that it exerts its biological effects acutely before its oxidation, pertinent to the close proximity of NETting neutrophils and pDCs in lupus-inflamed tissues." (PMID 34554930, 2021).